MIR661 (microRNA 661)
Synonyms: hsa-mir-661; MIRN661
Gene: MicroRNA gene on chromosome 8 (143,945,191 to 143,945,279, reverse strand). Ensembl gene ENSG00000207574.
Gene Ontology:
Biological process: miRNA-mediated post-transcriptional gene silencing
Cellular component: RISC complex